MTOR (mechanistic target of rapamycin kinase)
Diseases named in the same sentence as MTOR in open-access papers (continued):
Sharing a sentence is not in itself a finding about the gene and the disease.
pulmonary fibrosis (continued). "Leptin treatment can inhibit the activation of mTOR in the progression of pulmonary fibrosis, and mTOR is an important inhibitor of autophagy upstream." (PMID 31700697, 2019). "mTOR overactivation in alveolar epithelial cells and compromised autophagy in lungs contribute to the pathogenesis of pulmonary fibrosis." (PMID 30092799, 2018). "Recent studies have highlighted the pathological functions of mTOR-dependent autophagy in the development of pulmonary fibrosis." (PMID 29518028, 2018). "Studies also suggest that mTOR inhibitors are promising modulators of fibroproliferative diseases such as idiopathic pulmonary fibrosis (IPF) and radiation-induced pulmonary fibrosis (RIPF)." (PMID 29518028, 2018). "Romero found that idiopathic pulmonary fibrosis fibroblasts showed resistance to apoptosis, likely mediated by persistent mTOR activation." (PMID 29731718, 2018). "Levels of p-AKT and p-mTOR were also decreased in bleomycin-induced pulmonary fibrosis following treatment with ER stress inhibitors." (PMID 29079731, 2017). "Taken together, our data suggested that MALAT1-miR-503-PI3K/Akt/mTOR/Snail pathway plays critical roles in silica-induced pulmonary fibrosis." (PMID 28900284, 2017). "Immunohistochemistry also demonstrated that p-AKT and p-mTOR expression was decreased in the lungs of mice with bleomycin-induced pulmonary fibrosis following PI3K inhibitor treatment." (PMID 29079731, 2017). "Based on these findings, we concluded that miR-503 suppresses EMT by targeting PI3K/Akt/mTOR/Snail pathway in silica-induced pulmonary fibrosis." (PMID 28900284, 2017). "Western analysis of the silica-induced mouse lung fibrosis revealed that the variation trend of p-Akt, p-mTOR and Snail protein expression is similar with PI3K p85." (PMID 28900284, 2017). "The relationship between PI3K/AKT/mTOR and ER stress in pulmonary fibrosis, and the application of PI3K inhibitors and ER stress inhibitors in the treatment of pulmonary fibrosis require further investigation." (PMID 29079731, 2017). "In order to clarify the roles of Th17 cells and IL-17A+ γδ T cells in this model of pulmonary fibrosis, we utilized a cell-type specific deletion of the mTOR signaling protein raptor to selectively block generation of Th17 cells." (PMID 27649073, 2016). "Our data support that age‐related deficiency in adaptive responses to stress, together with an increased resistance to apoptosis of IPF lung fibroblasts, mediated by mTOR activity, enhances the vulnerability to lung fibrosis." (PMID 27566137, 2016). "Our study indicated that mTOR overactivation in AECs and autophagy dysfunction contributes to the pathogenesis of pulmonary fibrosis." (PMID 26382847, 2015). "We concluded that mTOR overactivation in AECs and compromised autophagy in the lungs are involved in the pathogenesis of pulmonary fibrosis." (PMID 26382847, 2015). "Rapamycin, an mTOR inhibitor, was reported to be effective in fibrotic diseases, including pulmonary fibrosis." (PMID 26382847, 2015). "The mammalian target of rapamycin (mTOR) signaling pathway in pulmonary fibrosis was investigated in cell and animal models." (PMID 26382847, 2015). "mTOR overactivation in AECs and dysfunctional autophagy involve in the pathogenesis of pulmonary fibrosis." (PMID 26382847, 2015). "Rapamycin and its analogues are reported to effectively prevent cardiac and pulmonary fibrosis in vivo, and mTOR promotes cell growth and proliferation by regulating protein synthesis." (PMID 25333576, 2015). "mTOR overactivation is involved in pathogenesis of pulmonary fibrosis via multiple cell types including AECs and fibroblasts." (PMID 26382847, 2015). "To investigate the role of mTOR signaling in AECs during the process of pulmonary fibrosis, we obtained transgenic SPC-rtTA/TetO-Cre/TSC1+/f (STT) mice by crossing three types of transgenic mice, SPC-rtTA, TetO-Cre and TSC1f/f, with each other." (PMID 26382847, 2015).
pulmonary fibrosis (continued). "Rapamycin attenuated bleomycin-mediated lung injury and death in mice, further supporting the idea that mTOR overactivation is involved in the process of pulmonary fibrosis." (PMID 26382847, 2015). "Our data further demonstrated that the mTOR inhibitor rapamycin attenuated bleomycin-mediated lung injury and mortality, which is consistent with a previous study exhibiting that mTOR inhibitors are effective for treating pulmonary fibrosis in animal models." (PMID 26382847, 2015). "There is growing evidence to support the idea that the mTOR signaling pathway plays a key role in pulmonary fibrosis." (PMID 26382847, 2015). "Our findings support a role for mTORC2 in the pathogenesis of lung fibrosis and for the potential of active site mTOR inhibitors in the treatment of IPF and other fibrotic lung diseases." (PMID 25162417, 2014). "In this study we set out to determine if blocking mTORC2 with MLN0128, an active site dual mTOR inhibitor, which blocks both mTORC1 and mTORC2, inhibits lung fibrosis." (PMID 25162417, 2014). "In support, inhibition of mTOR with rapamycin has been shown to prevent the initiation and propagation in a mouse model of TGFα-driven pulmonary fibrosis." (PMID 21660239, 2011). "In pulmonary fibrosis models, there is limited data on activation of mTOR and the effectiveness of rapamycin treatment." (PMID 21660239, 2011). "Consequently, oleuropein improves autophagic suppression and apoptotic resistance in fibroblasts during pulmonary fibrosis through the modulation of the TGF-β1/mTOR pathway." (PMID 41008517, 2025). "These reassuring findings indicate that TJ-5 may regulate autophagy through the PI3K/AKT/mTOR and MAPK/mTOR signaling pathways, and TJ-5-induced autophagy may reduce pulmonary fibrosis." (PMID 41007776, 2025). "In peimine‐containing compound herbal formulations, peimine inhibits M2 macrophage polarization by promoting autophagy through suppression of the serine/threonine‐protein kinase mTOR (mTOR) signaling suppression, thereby attenuating the development of pulmonary fibrosis." (PMID 40491981, 2025). "mTOR activity may be dysregulated in fibroblasts from individuals with idiopathic pulmonary fibrosis (IPF), leading to a fibroblast phenotype characterized by increased proliferation and resistance to apoptosis through alterations in autophagy activity." (PMID 41008517, 2025). "Additionally, studies in a rat model of idiopathic pulmonary fibrosis revealed that Angelica sinensis exerts its autophagy-inducing effects via modulation of the mammalian target of rapamycin (mTOR) pathway." (PMID 39881843, 2025). "Based on these findings, we aimed to determine whether MyD88 inhibition-induced autophagy in pulmonary fibrosis is related to mTOR, PI3K/AKT, and MAPK." (PMID 41007776, 2025). "Research has demonstrated that mTOR inhibition effectively attenuates pulmonary fibrosis." (PMID 41301772, 2025). "Tryptophan metabolites promote the progression of pulmonary fibrosis by activating the mTOR/S6 pathway, while modulation of certain microbial communities may slow down fibrosis by inhibiting these pathways." (PMID 41383739, 2025). "In conclusion, QFTL could effectively attenuate bleomycin-induced inflammation and pulmonary fibrosis through mTOR-dependent autophagy in rats." (PMID 38361765, 2024). "The expression of mTOR in the lungs of patients with idiopathic pulmonary fibrosis (IPF) exhibits a close correlation with fibrosis scores and diminished lung function, indicating its potential association with the prognosis of lung fibrosis." (PMID 38886743, 2024). "YAP1/TAZ activated or inhibited genes expression in the mitochondrial quality control pathway by binding to the promoter regions of mTOR, Raptor and mLST8, thereafter accelerating the fibroblast–myofibroblast differentiation and extracellular matrix deposition to promote pulmonary fibrosis." (PMID 38159063, 2024).
pulmonary fibrosis (continued). "In this study, immunohistochemistry and Western blot results showed that QFTL could significantly increase the expression of mTOR protein in bleomycin-induced pulmonary fibrosis in rats, while reducing the expression of the p62 protein." (PMID 38361765, 2024). "The results found that Duvelisib could regulate lung fibroblasts proliferation, migration, activation and autophagy by inhibiting the PI3K/Akt/mTOR signalling pathway, thereby attenuating pulmonary fibrosis." (PMID 36651446, 2023). "In addition, KD alleviates pulmonary fibrosis and effectively slows polycystic kidney disease progression through the inhibition of mTOR signaling." (PMID 37032786, 2023). "In addition, this work, for the first time, provides evidence that nintedanib improved oxidative stress, inhibited inflammatory response, and improved lung tissue apoptosis by downregulating PI3K/Akt/mTOR signaling pathway, ultimately improving lung fibrosis." (PMID 37160579, 2023). "Furthermore, mTOR increases autophagy and aggravates the progression of pulmonary fibrosis in silicosis under the regulation of AMP-activated protein kinase (AMPK)." (PMID 37381044, 2023). "We explored whether the protective effect of AMI on pulmonary fibrosis can be achieved by inhibiting the PI3K/Akt/mTOR signaling pathway." (PMID 37380638, 2023). "For instance, it remains unknown whether AMI inhibits pulmonary fibrosis by inhibiting the PI3K/Akt/mTOR pathway." (PMID 37380638, 2023). "Indeed, it has been widely reported that the Akt/mTOR pathway plays a master role in pulmonary fibrosis, and several Akt/mTOR inhibitors in development or in clinical trials have been reported to minimize clinical pulmonary fibrosis." (PMID 35624154, 2022). "The goal of this study was to see if N2FBR could reduce oxidative stress in BLM-induced lung fibrosis by triggering autophagy via the GSK-3β/mTOR pathway." (PMID 35903328, 2022). "Therefore, interventions aimed at restraining the activation of Smad, MAPK, and PI3K/Akt/mTOR signaling pathways provides an attractive strategy for a potent agent against pulmonary fibrosis." (PMID 36267283, 2022). "Activated AKT could phosphorylate mTOR, promoting the conversion of lung epithelial cells to fibroblasts, inducing lung fibrosis." (PMID 35707275, 2022). "Moreover, increasing evidences have affirmed that the impediment of activation of Smad-dependent and -independent cascades including MAPK and PI3K/Akt/mTOR pathways, which effectively inhibited pulmonary fibrosis induced by BLM." (PMID 36267283, 2022). "In addition, the inhibition of the PI3K/Akt/mTOR pathway can promote autophagy and improve pulmonary fibrosis." (PMID 35268069, 2022). "lncAP003419.16 is highly expressed in TGFβ1‐treated alveolar epithelial cells and IPF patients, in which lncAP003419.16 facilitates pulmonary fibrosis via the mammalian target of rapamycin (mTOR) signaling pathway dependent on its adjacent gene ribosomal protein S6 kinase B‐2 (RPS6KB2)." (PMID 33533071, 2021). "In particular, kidney transplant recipients treated with mammalian target of rapamycin inhibitors (mTOR-Is), particularly at high dosages, may develop pulmonary fibrosis." (PMID 34497515, 2021). "Furthermore, TGF-β is known to increase the activity of mTOR and ribosomal S6 kinase (p70S6K), a fibrosis-related factor, thereby promoting lung fibrosis." (PMID 33693011, 2021). "The mTOR/c-Myc axis plays an important role in the pathological process of pulmonary fibrosis." (PMID 35095515, 2021). "Our data suggest that protective effect of tetrandrine against lung fibrosis might be through promoting Rheb-mTOR and NRF2-SQSTM1 mediated autophagy." (PMID 34880752, 2021). "In addition, PI3K-Akt is also a bridge that communicates signals to various pathways, and it also plays an important role in pulmonary fibrosis, such as mTOR, VEGF, and TGF-β." (PMID 34395518, 2021). "However, enhancement of autophagy via blocking mTOR with rapamycin protected mice from pulmonary fibrosis." (PMID 34395518, 2021).
pulmonary fibrosis (continued). "In the lung tissues of patients with IPF, the expression level of autophagic protein p62 is higher than the normal value, and mTOR expression is closely related to the fibrosis score and decreased lung function, suggesting a possible relationship to the prognosis of pulmonary fibrosis." (PMID 33671452, 2021). "Furthermore, this study demonstrated that TSC1 was a functional target of miR-301a in fibroblasts, and the negative regulation of TSC1 by miR-301a promoted the severity of pulmonary fibrosis through the mammalian target of rapamycin (mTOR) signaling pathway." (PMID 32585629, 2020). "The findings revealed the crucial role of the miR-301a/TSC1/mTOR axis in the pathogenesis of pulmonary fibrosis, suggesting that miR-301a might serve as a potential therapeutic target." (PMID 32585629, 2020). "In addition, there is a number of in vitro studies that have underlined the link between the mTOR pathway and EMT in kidney, liver and lung fibrosis." (PMID 33409282, 2020). "Akt/mTOR-regulated autophagy may serve as a potential therapeutic option for the treatment of lung fibrosis." (PMID 32724454, 2020). "Indeed, stimulation of autophagy by rapamycin (an mTOR inhibitor promoting autophagic flux) significantly inhibits the fibrotic phenotype in bleomycin-induced pulmonary fibrosis." (PMID 30717487, 2019). "However, ligustrazin treatment significantly attenuated MDA and ROS levels, elevated Nrf2 and GSH expression, blocked mTOR activity, enhanced autophagy, and ameliorated PQ-induced pulmonary fibrosis." (PMID 30744607, 2019). "Future studies with clinically developable ATP-competitive mTOR inhibitors focused on determining their safety, efficacy, and therapeutic window in animal models of pulmonary fibrosis will be needed in order to further support the translatability of this approach for the treatment of IPF." (PMID 30602778, 2019). "Leptin promotes pulmonary fibrosis also by inhibiting autophagy via PI3K/Akt/mTOR pathway." (PMID 30806766, 2019). "In this study, PQ inhibited the PI3K/Akt/mTOR autophagy signalling pathway, enhanced Hh signalling by increasing ROS, upregulated Smo and Gli1 protein levels, promoted pro-Fibrin protein expression, and exacerbated PQ-induced lung fibrosis." (PMID 30744607, 2019). "mTOR mRNA levels in the lungs were elevated with PQ-induced pulmonary fibrosis." (PMID 30744607, 2019). "However, in the lung tissue leptin promotes pulmonary fibrosis development by inhibiting autophagy via PI3 K/Akt/mTOR pathway." (PMID 31700697, 2019). "Therefore, ligustrazin increased autophagy and improved PQ-induced pulmonary fibrosis by inactivating the AKT/mTOR signalling pathway by upregulating miR-193a." (PMID 30744607, 2019). "Decreased LC3-II expression and mTOR overactivation were observed in alveolar epithelial cells in bleomycin–induced pulmonary fibrosis mice model, as well as lung tissues from IPF patients compared to normal counterparts, suggesting impaired autophagic activity in IPF." (PMID 30717487, 2019). "There are thus several mTORC1, dual mTOR inhibitors and mixed mTOR/PI3K inhibitors in development or in clinical trials already that may be useful to minimize clinical pulmonary fibrosis." (PMID 29518028, 2018). "In this review, we discuss the pathological role of mTOR kinase in pulmonary fibrosis and examine how mTOR inhibitors may mitigate fibrotic progression." (PMID 29518028, 2018). "There is solid rationale to inhibit mTOR in pulmonary fibrosis, whether it is radiation-induced, drug-induced or idiopathic in nature." (PMID 29518028, 2018). "The mTOR expression in pulmonary fibrosis patients was significantly correlated with the fibrosis score and decreased lung function, indicating that it might be related to the prognosis of pulmonary fibrosis." (PMID 27438829, 2016). "Thus far, we demonstrated that mTOR overactivation in AECs is involved in the pathogenesis of lung fibrosis." (PMID 26382847, 2015).
pulmonary fibrosis (continued). "After obtaining strong evidence supporting our hypothesis that mTOR overactivation was involved in the process of pulmonary fibrosis, we further demonstrated that mTOR activation-related autophagy insufficiency could be a major mechanism." (PMID 26382847, 2015). "Growing evidences support the hypothesis that mTOR overactivation is involved in the pathogenesis of fibrotic diseases, including pulmonary fibrosis." (PMID 26382847, 2015). "The suppression of mTOR and enhancement of autophagy may be used for treatment of pulmonary fibrosis." (PMID 26382847, 2015). "Furthermore, we investigated the autophagy signaling pathway in a bleomycin-mediated lung fibrosis model, establishing a functional link between mTOR signaling and autophagy in lung injury and fibrosis." (PMID 26382847, 2015). "Using a conditional knock-down mouse model, we had the unique opportunity to explore whether aberrant mTOR signaling pathway in AECs plays a critical role in lung fibrosis." (PMID 26382847, 2015). "A previous study demonstrated that the initiation and progression of pulmonary fibrosis was prevented by the administration of rapamycin, an mTOR inhibitor, to a transgenic mouse with pulmonary fibrosis induced by lung-specific expression of the EGFR ligand, transforming growth factor (TGF)-α." (PMID 25358403, 2014). "Three proteins (mammalian target of rapamycin, mTOR; zinc finger E-box-binding homeobox 1, ZEB1; Rho-associated, coiled-coil containing protein kinase 1, ROCK1) may be related to pulmonary fibrosis." (PMID 25358403, 2014). "mTOR was mainly expressed in the alveolar epithelial cells of pulmonary fibrosis patients." (PMID 25358403, 2014). "However, the function of nintedanib on the P13K/Akt/mTOR pathway in regulating pulmonary fibrosis remains unknown." (PMID 37160579, 2023). "In addition, the AKT/mTOR/p70S6K pathway plays a vital role in airway inflammation and hypersensitivity, and phosphorylated p70S6K is involved in smooth muscle proliferation and pulmonary fibrosis." (PMID 37571300, 2023). "Therefore, C3G treatment might inhibit TGF‐β/mTOR signaling by the NRF2/HO‐1 pathway to alleviate SP‐induced pulmonary fibrosis." (PMID 35959254, 2022). "In addition, the activation of PI3K/Akt may be involved in the pathogenesis of pulmonary fibrosis by regulating its downstream molecules, such as mTOR and hypoxia-inducible factor-1 α." (PMID 35886594, 2022). "However, alternative evidence suggests that activation of the PI3K/Akt/mTOR pathway may contribute to pulmonary fibrosis and lung injury by regulating lung fibroblasts and epithelial cells." (PMID 35891565, 2022). "Hence, Ellagic acid could induce autophagy, and this process might be regulated by the Wnt/mTOR signaling pathway in pulmonary fibrosis." (PMID 33912053, 2021). "Therefore, inhibiting Wnt/mTOR signaling could promote autophagy formation, and this is an effective method to attenuate pulmonary fibrosis." (PMID 33912053, 2021). "Interestingly, mTOR inhibitors reversed this effect, therefore rapamycin could be considered a therapeutic agent in pulmonary fibrosis in SSc." (PMID 30806766, 2019). "However, the PI3K/Akt/mTOR autophagy signalling pathway was blocked by ligustrazin, which increased autophagy, decreased Hh signalling, downregulated Smo and Gli1 protein levels, suppressed pro-Fibrin expression, and ameliorated PQ-induced lung fibrosis." (PMID 30744607, 2019). "Therefore, mTOR represents an attractive and unique therapeutic target in pulmonary fibrosis." (PMID 29518028, 2018). "In conclusion, our findings demonstrate that HHT can effectively prevent and treat SiO2-induced pulmonary fibrosis in mice, primarily by inhibiting the PI3K/AKT/mTOR signaling pathway and CCR1 expression." (PMID 40396273, 2025). "In the bleomycin-induced rat model of lung fibrosis, the protein expression levels of PI3K, p-Akt, and p-mTOR in lung tissues are significantly elevated compared to the normal control group." (PMID 38886743, 2024).